PCGEM1 (PCGEM1 prostate-specific transcript)
Synonyms: NCRNA00071; LINC00071; PCAT9
Gene: Long non-coding RNA gene on chromosome 2 (192,749,803 to 192,776,899, forward strand). Ensembl gene ENSG00000227418.
Gene Ontology:
Biological process: regulation of apoptotic process
Diseases named in the same sentence as PCGEM1 in open-access papers:
PCGEM1 is named in the same sentence as 34 diseases in open-access papers, as found by Europe PMC text mining. Sharing a sentence is not in itself a finding about the gene and the disease. The quoted sentences say what the papers report.
prostate cancer (72 papers, 2009 to 2024). A primary or metastatic malignant tumor involving the prostate gland. "The lncRNA PCGEM1 has been found to be associated with the incidence of prostate cancer (PCa) and can promote the progression of PCa." (PMID 36915057, 2023). "The overexpression of PCGEM1, as a prostate-specific lncRNA, was correlated with high risk of prostate cancer." (PMID 36438902, 2022). "For instance, the PCA3 (also called DD3) and PCGEM1 were the first lncRNAs that were associated with cancer because they were overexpressed in prostate cancer." (PMID 31448238, 2019). "Two SNPs, rs6434568 and rs16834898, within the PCGEM1 gene are associated with prostate cancer risk in Chinese men, with the C at rs6434568 and A at rs16834898 as risk alleles, respectively." (PMID 28598379, 2017). "Lastly, another lncRNA, prostate cancer gene expression marker 1 (PCGEM1) is also overexpressed in prostate cancer, and associated with reduction in chemotherapy-induced apoptosis." (PMID 26978351, 2016). "The pathogenic role of PCGEM1 in prostate cancer was further indicated by its ectopic expression in LNCaP and NIH3T3 cells, which resulted in hyperproliferation." (PMID 26935426, 2016). "Another example is PCGEM1, which is prostate tissue-specific and prostate cancer-associated, and whose overexpression promotes cell proliferation." (PMID 26760768, 2016). "PCGEM1 is a prostate tissue-specific gene encoded on chromosome 2q32 that serves as a prostate cancer gene expression marker." (PMID 26110379, 2015). "In androgen-refractory prostate cancer, PRNBR1 and PCGEM1 are robustly expressed and are implicated in the ligand-independent activation of AR signaling [AR “resistant” prostate cancer]." (PMID 24723937, 2014). "Two tagSNPs (rs6434568 and rs16834898) of the PCGEM1 were reported to be associated with prostate cancer." (PMID 23843741, 2013). "A prostate-specific lncRNA, PCGEM1, is associated with prostate cancer and regulates apoptosis, while RNAseq has uncovered a second lncRNA in prostate cancer progression." (PMID 23577021, 2013). "Two lncRNAs, PRNCR1 and PCGEM1, are found to be overexpressed in different prostate cancers and cause the androgen receptor (AR)–associated transcriptional mechanisms to induce the growth of prostate cancer." (PMID 36359888, 2022). "Prostate cancer gene expression marker 1 (PCGEM1) encodes a prostate-specific long non-coding RNA (lncRNA) that has oncogenic activity in prostate cancer; polymorphisms in PCGEM1 have been linked to prostate cancer risk." (PMID 28035996, 2016). "However, how these SNPs contribute to the risk of prostate cancer through PCGEM1 is still unclear." (PMID 28598379, 2017). "In prostate cancer, genome-wide RNA-Seq analysis identified many lncRNAs that are up- or down-regulated in prostate cancer, such as PCA3, PCGEM1, and PCAT-1 are highly associated with prostate cancer." (PMID 39403375, 2024). "A new long noncoding RNA (lncRNA), prostate cancer gene expression marker 1 (PCGEM1), is located on chromosome 2q32.3, which is overexpressed in prostate cancer." (PMID 38948025, 2024). "As a carcinogenic lncRNA, PCGEM1 contributed to the occurrence and development of prostate cancer, ovarian cancer, endometrial carcinoma, and gastric cancer." (PMID 38948025, 2024). "Recent studies have revealed that PCGEM1 acts as an oncogene in many cancers, including prostate cancer, ovarian cancer, gastric cancer and renal cancer." (PMID 36915057, 2023). "The inhibition of prostate-specific transcript 1 (PCGEM1) upregulates miR-145 expression, inhibiting the proliferation and xenograft tumor growth of prostate cancer cells." (PMID 37190145, 2023). "Baicalein also suppresses prostate cancer proliferation through inhibiting lncRNA, decreasing PCGEM1 expression and inducing cell autophagy." (PMID 37940982, 2023). "Initially, PCGEM1 was uncovered as an emerging noncoding RNA in prostate cancer and was found to be overexpressed in a significant proportion of tumor tissues." (PMID 35265529, 2022).
prostate cancer (continued). "Further research showed that cotransfection of a miR-506-3p inhibitor with a TRIAP1 overexpression plasmid restored the suppressive effect of PCGEM1 knockdown on the proliferation, migration and invasion of prostate cancer." (PMID 35109849, 2022). "Further research demonstrated that PCGEM1 was negatively correlated with the expression of miR-506-3p in prostate cancer tissues, and PCGEM1 directly regulated the expression of miR-506-3p." (PMID 35109849, 2022). "In summary, we demonstrated for the first time that PCGEM1 were upregulationed in prostate cancer and cell lines." (PMID 35109849, 2022). "Our study confirmed that PCGEM1 can be used as a biomarker for the early diagnosis of prostate cancer and can also be used as a clinical target to treat prostate cancer." (PMID 35109849, 2022). "As one of the earliest oncogenic lncRNAs discovered in prostate cancer, PCGEM1 has received increasing attention in recent years." (PMID 35265529, 2022). "and knockdown of PCGEM1 inhibited the proliferation, migration and invasion of PC-3 and C4-2B prostate cancer cells in vitro and in vivo." (PMID 35109849, 2022). "LncRNA PCGEM1 has been identified as a carcinogenic molecule and has been studied in ovarian cancer, cervical cancer, gastric cancer and prostate cancer." (PMID 35109849, 2022). "The prostate cancer gene expression marker (PCGEM1) is one of the first carcinogenic lncRNAs to be identified and upregulated in many cancers, including cervical carcinoma." (PMID 33805687, 2021). "PCGEM1 is also upregulated in prostate cancer cells, and its inhibition induces apoptosis and enhances the sensitivity of LNCaP cells to doxorubicin (DOX)." (PMID 33805687, 2021). "When endogenous PCGEM1 is knocked down, the activity of c-Myc will decrease, indicating that PCGEM1 plays a metabolic regulation role as a co-activator of c-Myc in prostate cancer cells." (PMID 33849550, 2021). "Other lncRNAs such as Prostate Cancer Gene Expression Marker 1 (PCGEM1) are involved in the regulation of metabolic genes acting as coactivators of the androgen receptor." (PMID 34298698, 2021). "For example, PCGEM1 is highly expressed in prostate cancer cells, and it can accelerate the progression of prostate cancer through sponging miR-145." (PMID 32787827, 2020). "For instance, lncRNAs PCAT8 and PCGEM1 are highly overexpressed in aggressive prostate cancer and strongly enhance androgen-receptor-mediated gene activation and proliferation in prostate cancer cells." (PMID 32849794, 2020). "PCGEM1-overexpressing prostate cancer cells showed an increase in the cellular level of citrate, indicating enhanced fatty acid synthesis." (PMID 33123488, 2020). "PCGEM1 is an lncRNA and it has been reported to facilitate the development of some cancers, such as prostate cancer, endometrial carcinoma and ovarian carcinoma." (PMID 32787827, 2020). "The similar prognostic value of PCGEM1 was also found in gastric cancer, ovarian cancer and prostate cancer." (PMID 31832017, 2019). "It has been demonstrated that DIM inhibits PCGEM1 expression and induces apoptosis in prostate cancer." (PMID 31208095, 2019). "Prostate cancer gene expression marker 1 (PCGEM1) is an lncRNA that is initially found to be overexpressed in aggressive prostate cancers." (PMID 30486435, 2018). "Prostate cancer gene expression marker 1 (PCGEM1) is an androgen-induced prostate-specific lncRNA whose overexpression is highly related to prostate cancer." (PMID 30134946, 2018). "Next, lncRNA with significantly lowered expression is PCGEM1, which functions as biomarker of prostate cancer." (PMID 30441874, 2018). "In prostate cancer, plenty of LncRNAs, including PCGEM1, SOCS2-AS1, PlncRNA-1, CTBP1-AS, DRAIC and PCAT29, have been reported to be associated with AR pathway, and thus act as regulators in the development of PCa." (PMID 28771526, 2017).
prostate cancer (continued). "In prostate cancer, prostate cancer gene expression marker 1 (PCGEM1) is a long coding RNA that can interact with MYC directly and enhance its activity." (PMID 28362357, 2017). "In this regard, we found a positive correlation of PCGEM1 with AR3, a major splice variant, in prostate cancer cell lines." (PMID 26848868, 2016). "In support of this possibility, PCGEM1 is correlated with AR3, a predominant and clinically important form of AR splice variants in prostate cancer." (PMID 26848868, 2016). "A very recent study has shown the splicing of AR-V7 in prostate cancer cells is controlled by PCGEM1 via its interaction with splicing factors hnRNP A1 and U2AF65." (PMID 28035996, 2016). "PCGEM1 was identified as a prostate cancer specific lncRNA that is capable of promoting proliferation and inhibiting apoptosis." (PMID 26848868, 2016). "PCGEM1 is an interesting molecule, but the role of PCGEM1 in prostate cancer is still controversial." (PMID 26848868, 2016). "PCGEM1 was found to have ethnic-specific expression, being much higher in the prostate epithelial cells of African-American prostate cancer patients compared to Caucasian patients." (PMID 26935426, 2016). "PCGEM1 over-expression promotes proliferation and colony formation and inhibits doxorubicin-induced apoptosis in prostate cancer cells." (PMID 26110379, 2015). "PCGEM1 (prostate cancer gene expression marker 1), a long noncoding RNA, has a significantly higher expression level in prostate cancer cells in African-American men." (PMID 26110379, 2015). "PCGEM1 (Prostate Cancer Gene Expression Marker), 1.6 kb in size, derived from the 2q32 locus, it is one of the earliest oncogenic lncRNAs discovered." (PMID 26082843, 2015). "PCGEM1 is highly elevated in prostate cancer, especially in patients with a family history of prostate cancer." (PMID 26082843, 2015). "Accordingly, PCGEM1 and PRNCR1 were implicated in progression of prostate cancer (PCa) as transcriptional co-regulators of the androgen receptor (AR)." (PMID 25744782, 2015). "In the male reproductive system, prostate cancer gene expression marker 1 (PCGEM1) has been demonstrated as a prostate tissue-specific, and prostate cancer-associated noncoding RNA (ncRNA) gene." (PMID 26055877, 2015). "The results shows that shows that reduce the expression of PCGEM1 or over express miR-145 can effectively inhibit prostate cancer growth in vivo." (PMID 25200485, 2014). "LNCaP tumor xenografts were established in Athymic nude mice to evaluate the effects of siRNA PCGEM1 or pmiR-145 on prostate cancer growth in vivo." (PMID 25200485, 2014). "While PCGEM1 has been observed in prostate cancer previously, PRNCR1 is a poorly characterized transcript, and we were concerned that PRNCR1 had been nominated by previous global profiling studies of prostate cancers." (PMID 24727738, 2014). "In summary, we have been unable to show a convincing role for PCGEM1 or PRNCR1 in aggressive prostate cancer or AR signaling." (PMID 24727738, 2014). "Both downregulation of PCGEM1 or overexpression of the miR-145 reduced the proliferation and invasive capacity of prostate cancer cells in vitro and in vivo." (PMID 25200485, 2014). "Prostate cancer gene expression marker 1 (PCGEM1) is a long non-coding RNA (lncRNA) overexpressed in prostate cancer (PCa) cells that promotes PCa initiation and progression, and protects against chemotherapy-induced apoptosis." (PMID 25200485, 2014). "In this study, we explored possible mutual regulation of PCGEM1 and miR-145 expression in prostate cancer and the impact on PCa cell proliferation and invasive capacity." (PMID 25200485, 2014). "In turn, Reciprocal regulation of PCGEM1 and miR-145 promote proliferation of LNCaP prostate cancer cells." (PMID 25200485, 2014). "The effect of siRNA PCGEM1 and miR-145 transfection on prostate cancer growth in vivo was examined in the (nu/nu) mouse model." (PMID 25200485, 2014).
prostate cancer (continued). "Further, two lncRNAs termed PRNBR1 and PCGEM1 that are upregulated in aggressive prostate cancer, synergistically and coordinately bind the carboxyterminal part of the androgen receptor (AR) and are required for AR-dependent gene transcription." (PMID 24723937, 2014). "Accordingly, 3,30-dindolylmethane may suppress the proliferation of prostate cancer cells by regulating the PCGEM1–miR-145 axis." (PMID 37190145, 2023). "Additionally, studies have shown that PCGEM1 (prostate cancer gene expression marker 1) inhibits apoptosis by suppressing Caspase 7 activation, leading to doxorubicin resistance in prostate cancer." (PMID 37509693, 2023). "This suggests that PCGEM1 promotes prostate cancer cell proliferation by sponging miR-145." (PMID 37190145, 2023). "Prostate cancer gene expression marker 1 (lncRNA PCGEM1) was first reported in prostate cancer." (PMID 36193492, 2022). "Several reports support that PCGEM1 is an oncogene in prostate cancer." (PMID 33589577, 2021). "PCGEM1 is discovered to promote prostate cancer progression." (PMID 33589577, 2021). "The function of PCGEM1 is mainly researched in prostate cancer." (PMID 33589577, 2021). "In addition to regulating glucose metabolism PCGEM1 widely regulates metabolic gene expression, including lipid metabolism in prostate cancer cells." (PMID 33123488, 2020). "The overexpression of the lncRNA prostate cancer gene expression marker 1 (PCGEM1) produces resistance to DOX-induced apoptosis by suppressing the cleavage of caspase - 7 in LNCaP (cancer cells isolated from the lymph node of a patient with prostate cancer)." (PMID 32164712, 2020). "PCGEM1 overexpression increases glucose uptake and lactate production along with the pentose phosphate shunt to provide a sufficient supply of nucleotides and lipids in prostate cancer." (PMID 33123488, 2020). "PCA3 might be used as a biomarker for the diagnosis of prostate cancer and PCGEM1 involved in c-MYC activation and androgen receptor transcriptional activation was associated with the progression of prostate cancer." (PMID 31448238, 2019). "Resveratrol inhibits the AR signaling pathway in prostate cancer by affecting PCGEM1 and PRNCR1." (PMID 31208095, 2019). "PCGEM1 was first found to be highly expressed in prostate cancer and promotes cell proliferation." (PMID 31832017, 2019). "For example, PCGEM1 is highly up-regulated in prostate cancers, and it could promote prostate cancer cell proliferation." (PMID 28423699, 2017). "PCGEM1 is a long non-coding RNA (lncRNA) that is often upregulated in prostate cancer." (PMID 27682980, 2016). "Some years later, PCGEM1 was patented as a promising biomarker for prostate cancer." (PMID 26935426, 2016). "We speculate that reciprocal regulation of PCGEM1 and miR-145 promote proliferation of LNCaP prostate cancer cells." (PMID 25200485, 2014). "Next, an independent analysis of 235 high-risk prostate cancer tissues demonstrated that neither PCGEM1 nor PRNCR1 is associated with aggressive prostate cancer, and neither lncRNA stratifies prostate cancer-specific mortality." (PMID 24727738, 2014). "We therefore sought to investigate PRNCR1 and PCGEM1 in prostate cancer." (PMID 24727738, 2014). "Through a comprehensive analysis of RNA-sequencing data (RNA-seq), we find evidence that PCGEM1 but not PRNCR1 is associated with prostate cancer." (PMID 24727738, 2014). "Using an independent validation cohort of tissues we verified that neither PCGEM1 nor PRNCR1 is associated with aggressive prostate cancer." (PMID 24727738, 2014). "First, our data analysis of numerous human prostate cancer tissues from multiple independent laboratories indicates that neither PCGEM1 nor PRNCR1 are associated with castration-resistant prostate cancer." (PMID 24727738, 2014). "An lncRNA prostate cancer gene expression marker 1 (PCGEM1) is overexpressed in prostate cancer." (PMID 23843741, 2013).